BRAF (B-Raf proto-oncogene, serine/threonine kinase)
Diseases named in the same sentence as BRAF in open-access papers (continued):
Sharing a sentence is not in itself a finding about the gene and the disease.
tumor (continued). "In this model, over 90% of proliferative tumor cells were positive for SOX2 (a stem cell marker) and pERK1 + /ERK2 + (downstream mediators of BRAF and major effectors of MAPK)." (PMID 40696244, 2025). "This is also reminiscent of the sensitization of BRAF and other MAPK pathway activation tumor models to MAPK pathway inhibitors via the suppression of YAP134,35,38." (PMID 39856157, 2025). "A combination of BRAF p.V600E and MEK inhibitors has demonstrated significantly improved survival parameters in a wide spectrum of tumour types." (PMID 38773787, 2025). "Although they did not delineate the dose–response relationship of BRAF V600E mutation abundance, they proposed that BRAF mutation abundance could serve as an indicator for preoperative assessment of tumor aggressiveness and determination of surgical extent, which is consistent with our findings." (PMID 41228353, 2025). "The principal differences in tumor growth pattern – papillary versus follicular – is intriguing and cannot easily be attributed to the differential pathogenicity of mutant RAS and BRAF of which both confer constitutive activation of the MAPK signaling pathway." (PMID 39956582, 2025). "The upstream MAPK pathway activates downstream ERK through KRAS and BRAF, and collaborates with the PI3K/AKT pathway to enhance the proliferation of tumor cells." (PMID 40989695, 2025). "The absence of an association with tumor location (left vs. right) also differs from the well-established connection between BRAF mutations and right-sided tumors, which may reflect the small number of BRAF-mutant cases in this cohort or unique etiological factors." (PMID 41439081, 2025). "Tumor growth was monitored, and molecular analyses included RNA sequencing and immunofluorescence quantification of PI3K, AKT1, mTOR, ERBB2, BRAF, and MITF protein levels, and molecular docking simulations were performed." (PMID 40806647, 2025). "The systemic therapy only frequency was 41–64% according to primary tumour location, RAS-, BRAF-, and MMR-status, with a markedly variable mOS of 6–23 months, which cannot be explained by the minor differences in systemic therapy intensity in the subgroups." (PMID 40437037, 2025). "However, the presence of BRAF or FGFR mutations could suggest that the tumor aligns more closely with an AFO rather than a (developing) complex odontoma." (PMID 39907837, 2025). "As predicted, the combined treatment of BRAF PTEN mice with AZD6244/AZD8186 was highly effective, resulting in attenuated tumor growth, tumor regression over the first 7 days of treatment, and extended overall survival." (PMID 39636745, 2025). "Although BRAF/MEK inhibitors are generally well-tolerated, some patients have experienced severe adverse events, and tumor recurrence has been reported after drug cessation, raising concerns about long-term safety in broader patient populations." (PMID 40696244, 2025). "This population-based cohort shows that primary tumour location, RAS/BRAF-status, and MMR-status affect clinical characteristics, treatability, and outcome of mCRC." (PMID 40437037, 2025). "Co-inhibition of BRAF and its downstream target MEK has been shown to synergistically heighten anti-tumor efficacy and forestall drug resistance." (PMID 41480531, 2025). "Key markers such as KRAS, BRAF, MSI, and tumor differentiation offer valuable insights into tumor behavior and prognosis." (PMID 40740242, 2025). "In cases with sufficient tissue, we performed BRAF V600E immunohistochemistry (IHC) and BRAF next generation sequencing (NGS) of extracted tumour DNA." (PMID 39900703, 2025).
tumor (continued). "BRAF and MEK inhibitors, for instance, have been shown to increase levels of interferon-γ (IFN-γ) and promote T cell activation, leading to enhanced tumor infiltration by CD8 + T cells." (PMID 39757310, 2025). "BRAF inhibitor drugs, such as dabrafenib and vemurafenib, inhibit BRAF mutants at the ATP binding site, which impedes BRAF signaling in the MAPK pathway, suppressing tumor growth." (PMID 41355975, 2025). "More and more publications are devoted to the issues of adding BRAF, MEK, or MTOR inhibitors to standard MM therapy for targeting the tumor cell." (PMID 40943426, 2025). "This, in turn, upregulates oncogenes such as BRAF and RAS, activates the MAPK/ERK signaling pathway, and facilitates tumor progression." (PMID 40723913, 2025). "This case report highlights the potential value of early integration of PD-1 blockade with BRAF/MEK inhibition therapy in selected, high tumor burden cases." (PMID 41333480, 2025). "The RAS/RAF/MEK/ERK and PI3K/AKT/mTOR cascades represent key signaling routes whose dysregulation contributes to tumor growth, survival, and therapeutic resistance in tumors harboring alterations such as KRAS, BRAF, PIK3CA, or PTEN." (PMID 41465387, 2025). "Triple therapy with Remodelin, cetuximab, and 5-Fluorouracil enhanced tumor regression in xenograft mouse models of CRC with wild-type KRAS, NRAS and BRAF." (PMID 39905540, 2025). "The introduction of combined BRAF and MEK inhibition dramatically improves survival outcomes; however, despite initial tumor regression, most patients eventually relapse, and median progression-free survival rarely exceeds 12–18 months." (PMID 40872623, 2025). "The combination of BRAF/MEK inhibitors with the peroxisome proliferator-activated receptor (PPAR) agonist, thioridazine, produces a synergistic anti-tumor response in the xenograft model." (PMID 41155168, 2025). "This leaves some BRAF molecules active, allowing the MAPK pathway to continue functioning and promoting tumor cell growth despite the inhibitor’s presence." (PMID 40872623, 2025). "Inhibiting ERK1/2 in the BRAF pathway decreases fibronectin secretion, and combining BRAF and ERK1/2 inhibitors slows tumor growth and reduces fibronectin levels." (PMID 40129883, 2025). "addressed the heterogeneity of the mutations predicting the resistance to anti‐EGFR treatment (KRAS, NRAS, BRAF and/or PIK3CA) in the primary CRC tumours in the context of the proportion of neoplastic cells." (PMID 40302146, 2025). "Subsequent research found that analysing a single tumour block resulted in inaccurate KRAS and BRAF status in 10%–30% of cases, requiring multi‐region analysis." (PMID 40302146, 2025). "Reduced RICTOR expression resulted in elevated NAMPT expression and increased mitochondrial respiration, contributing to the intrinsic tolerance of drug-naïve tumor cells to BRAF/MEK inhibition and fostering a BRAF inhibitor-resistant phenotype." (PMID 40775221, 2025). "This mRNA-based CNV profile of the primary tumour closely resembled that obtained from DNA methylation data, including the presence of amplification of the chromosome bands encompassing MITF and BRAF." (PMID 41168392, 2025). "These tumor markers include IDH1 R132, IDH2 R172, pTERT C228 and C250, H3F3A K27/G34, Hist1H3B K27, and BRAF V600." (PMID 39606159, 2024). "High-level activation of oncogenes (e.g., KRAS, BRAF, and c-MYC) triggers intrinsic tumor suppression 46,50–53." (PMID 36778401, 2024). "The lethal-7 (let-7) family, miR-143-145 cluster, and miR-34a have been described to be tumor suppressive miRNAs that decelerate CRC progression through the downregulation of oncogenes such as RAS, c-Myc, and BRAF." (PMID 39202367, 2024). "Encorafenib, a small-molecule BRAF inhibitor, disrupts the MAPK/ERK signaling pathway, leading to decreased tumor cell proliferation and survival." (PMID 39684219, 2024).
tumor (continued). "It is important to note that while three of the four subclones harboring both BRAF and NEDD4L insertions were detected within the same tumor mass, each subclone is defined by completely independent transposon insertion events." (PMID 38213996, 2024). "The inter-group expression difference analyses for tumor genes implied that APC, ATM, BARD1, BRAF, and BRCA1 gene expression varied among patients in these two groups." (PMID 38338834, 2024). "A case report of unresectable BRAF-wildtype ATC with programmed death-ligand 1 (PD-L1) expression >90%, in which treatment with lenvatinib and pembrolizumab for one month allowed tumor resection, achieved disease stability for at least 11 months." (PMID 39407830, 2024). "Previous studies indicate that simultaneous inhibition of BRAF and MEK or MAPK induces pyroptosis in tumor cells, thereby enhancing the immune responses." (PMID 38424542, 2024). "Moreover, answering these questions will be key for a successful targeted therapy as an incomplete inhibition of a highly active BRAF oncoprotein triggering OIS instead of cell death in the majority of tumor cells might allow cell cycle re-entry and tumor expansion instead." (PMID 38789691, 2024). "An incomplete tumor “capsule”, indicative of infiltrative tumor growth, has been identified as an imaging marker for predicting MVI and high BRAF and RAF1 expression in HCC, which can promote tumor invasion and metastasis." (PMID 38763975, 2024). "Paradoxically, these drugs enhance Class II and III altered BRAF signaling, in which dimerization promotes enhanced MAPK signaling and ultimately tumor growth." (PMID 39018217, 2024). "Median follow-up was 49.4 months, 8.7% had acral cutaneous melanoma, 50% were BRAF-positive, 79.9% were LAG-3 positive, 26.1% were tumor PD-L1-positive and 6.5% received prior adjuvant therapy." (PMID 39727691, 2024). "Furthermore, although RET point mutation co-occurs with BRAF V600E mutation, the mutation abundance of BRAF V600E was significantly lower than that of RET point mutation, suggesting that a large proportion of tumor cells have only RET point mutation but no BRAF V600E mutation." (PMID 38734621, 2024). "Consistent with these genomic observations, abundant pre-clinical evidence across many malignancies indicates that BRAF alterations drive an increase in MAPK signaling and, thus, tumor growth in cancer cell lines and transgenic mouse models." (PMID 39018217, 2024). "One limitation of BRAF and MAPK/ERK pathway inhibitors in general is their failure to induce substantial levels of apoptosis in CRC and other tumour cell types." (PMID 38429301, 2024). "For example, this study demonstrates the potential role of NG2 in alleviating BRAF inhibitor resistance by cell line, NG2-knockout xenograft tumor model and thyroid-specific NG2 knockout mouse model." (PMID 38795180, 2024). "We report that the level of intratumoral DAG determines the response of anti-BRAF/EGFR therapy in BRAFV600E-mutant mCRC, enriching our understanding of DAG’s regulation of tumor-targeted therapy." (PMID 39436710, 2024). "On the other hand, TEAD can play an important role in tumor progression, metastasis, tumor metabolism, immunity and drug resistance through transcription and regulation of KRAS, BRAF, LKB1, NF2 and MYC." (PMID 38553612, 2024). "Regorafenib, a novel oral multi-kinase inhibitor, disrupts kinases involved in tumor angiogenesis (VEGFR1, VEGFR2, VEGFR3, TIE2), tumorigenesis (KIT, RET, RAF1, BRAF, and BRAFV600E), and the tumor microenvironment (PDGFR and FGFR)." (PMID 39687893, 2024). "Given that the BRAF mutation strongly drives MAPK pathway activity, there may be synergistic benefits between genomic drivers and high levels of inflammation when using immunotherapy to treat this group of patients that is at high risk of progression from their tumor." (PMID 38987542, 2024).
tumor (continued). "By inhibiting mutant BRAF, dabrafenib disrupts the MAPK/ERK signaling pathway, leading to reduced cell proliferation and potential apoptosis of tumor cells." (PMID 39654184, 2024). "High-level activation of oncogenes (e.g. KRAS, BRAF, and c-MYC) triggers intrinsic tumor suppression." (PMID 38921956, 2024). "The drugs Dabrafenib and Trametinib, targeting BRAF and MEK1/2 respectively, work by inhibiting tumor cell proliferation through disruption of the RAF-MEK-ERK signaling pathway." (PMID 39027479, 2024). "In this study, the impact of BRAF inhibitors and Ultraviolet B (UVB) light on tumor growth was investigated in laboratory mice after infection of their skin with a murine papillomavirus." (PMID 39335105, 2024). "An increased efficacy has been observed when the simultaneous inhibition of BRAF and MEK proteins is used, with significant overall survival benefits and accelerated tumor regression." (PMID 39684531, 2024). "Many clinically used chemotherapeutics, such as paclitaxel, doxorubicin, cisplatin, BRAF inhibitors, MEK inhibitors, and sorafenib, have been reported to induce pyroptosis in tumor cells as part of their antitumor mechanisms." (PMID 39335166, 2024). "Some authors also propose the use of neoadjuvant BRAF/MEK inhibitors in patients with neurological deficit, to benefit from the rapid tumour shrinkage.The timing of administration should be tailored to each patients’ characteristics." (PMID 39456573, 2024). "Treatment with a combination of a BRAF inhibitor and a MEK inhibitor is a strategy that moderates the effects of tumor heterogeneity and thus results in better PFS of patients compared to BRAF inhibitor monotherapy." (PMID 39272837, 2024). "Our findings strongly suggest that standard chemotherapy and targeted therapy inhibiting BRAF/MEK and EGFR impose quite different selection pressures on the tumor cells." (PMID 39626159, 2024). "We observed a significant tumor-suppressive effect in xenograft tumors treated with a combination of I3C and SHP099 in SW620 (KRAS-mutant), RKO (BRAF-mutant), and Caco-2 (wild type) cells." (PMID 39014007, 2024). "Given that anti-EGFR therapy is effective exclusively in individuals with KRAS or BRAF wild-type tumors, the wild-type status of KRAS and BRAF in the tumor assumes significance." (PMID 38791280, 2024). "Other novel immunotherapy strategies have also been evaluated for complimentary effects to BRAF inhibitors, including oncolytic HSV and CAR T-cell therapy, both of were shown to enhance tumor control in pre-clinical models." (PMID 38275291, 2024). "Previous studies have reported that a right colon PTL is associated with a lack of benefit when treated with EGFR-inhibitors; additionally, when the tumor is RAS wt or RAS & BRAF wt and pMMR." (PMID 38473410, 2024). "Neoadjuvant systemic therapy with BRAF and MEK inhibitors (Dabrafenib and Trametinib) was initiated to reduce tumor size." (PMID 39767221, 2024). "The FOLFOXIRI plus cetuximab regimen displayed tolerable toxicity and promising anti-tumor activity in terms of the rate of NED achieved and response rate in patients with initially unresectable left-sided RAS/BRAF wild-type CLM." (PMID 38638850, 2024). "For this purpose, we prepared tumor slice cultures from ten PDX tumors of NSG mice, all derived from BRAF-WT metastases of patients." (PMID 38263136, 2024). "Since the source of cfDNA composition of liquid biopsies includes both tumor and normal tissues, we used KR121 and KR125 to detect both mutant and WT BRAF, respectively." (PMID 39644903, 2024). "Recently, dabrafenib, a BRAF inhibitor, in combination with trametinib, an MEK inhibitor, received tumor-agnostic approval for advanced solid malignancies harboring BRAF V600E." (PMID 38791902, 2024).
tumor (continued). "The prognostic determinants examined included clinicopathological features such as tumor stage, grade, and lymph node involvement, as well as molecular biomarkers including RAS, BRAF, and MSI status." (PMID 39682117, 2024). "Targeted therapies, including inhibitors targeting BRAF, MEK, c-KIT, and NRAS, are designed to block the specific molecules responsible for tumor growth." (PMID 38399429, 2024). "Regorafenib is an oral multi-targeted TKI, whose targets are involved in the regulation of tumor angiogenesis (VEGFR1–3 and TEK), oncogenesis (KIT, RET, RAF1, BRAF, and and BRAFV600E), and maintenance of the tumor microenvironment (PDGFRA, PDGFRB and FGFR)." (PMID 39165680, 2024). "Recent studies have shown that targeted oncogene therapy, which includes inhibitors of EGFR, ALK, KRAS, and BRAF, induces DNA double-strand breaks and activates the DDR pathway in residual tumor cells." (PMID 38776912, 2024). "This goes hand in hand with the availability of modern adjuvant therapies based on targeted therapy with BRAF and MEK inhibitors or anti‐tumor immunotherapy using PD1 checkpoint inhibitors." (PMID 39387479, 2024). "Additionally, BRAF inhibitors may downregulate the expression of immune checkpoint molecules on the surface of tumor cells, such as PD-L1, which helps to relieve the immunosuppression imposed by the tumor and enhances the anti-tumor activity of T cells." (PMID 39529955, 2024). "Recently, the FDA granted tumor-type agnostic approval of dabrafenib and trametinib, BRAF and MEK inhibitors, for the treatment of any metastatic BRAF V600E mutant cancer." (PMID 38275886, 2024). "We observed that both the tumor cell-intrinsic and immune cell-intrinsic RIG-I responses are functional under combined BRAF/MEK inhibitor therapy." (PMID 39165562, 2024). "The results show that BRAF, CDKN1A, DIABLO, PEA15, ERRFI1, and RPS6KB1 are highly expressed in tumor cell lines, which is the same as in the TCGA database." (PMID 39239554, 2024). "While there is no recurrent gene amplification that was observed, the following genes were amplified in two tumor samples: MET, SMO, ERBB2, BRAF, EZH2, SRSF2, CUX1, and CEBPA." (PMID 38164123, 2024). "The tumour MSS status for the experimental-arm CR cases was verified using complementary assays; five were females ≥60 years with right-sided primary tumour and all six were RAS/BRAF-mutant cases." (PMID 38664577, 2024). "Oncogenic activity of oncogenes promoting tumor growth such as RAS and V‐Raf murine sarcoma viral oncogene homolog B (BRAF) seems to increase autophagy levels, indicating a link between autophagy and tumor progression." (PMID 36760166, 2023). "In cohort 2, 100 FFPE tumour specimens from CRC patients previously analyzed by ME-PCR and DS were retrospectively tested by the SensiScreen® FFPE BRAF qPCR simplex Assay." (PMID 36758042, 2023). "In the last few years more and more drugs, such as TRK, ALK, checkpoint, and BRAF, as well as FGFR, inhibitors have been or are being evaluated in basket clinical trials, with some of them already formally approved as tumor agnostic therapies." (PMID 38098111, 2023). "Among patients with an RAS-Mut tumor, 1.1% received EGFR inhibitors and 59.7% received VEGF inhibitors and, among those with a BRAF-Mut tumor, 6.3% received EGFR inhibitors and 57.2% received VEGF inhibitors." (PMID 36656585, 2023). "For half of the biomarkers (AKT, ALK, BRAF, EGFR, Hedgehog, HER2, KRAS, MSI, NTRK, and ROS1), depending on the tumor type, the response rate ranged from 0 to 100%." (PMID 36639625, 2023). "Other genes that have been studied in rectal cancer with contrasting results include BRAF, PIK3CA, SMAD4, and tumor MSI." (PMID 36900260, 2023). "This study also proposed YAP1 upregulation as a biomarker of poor initial response to BRAF and MEK inhibition in BRAFV600E tumor patients." (PMID 37834284, 2023).